MTOR (mechanistic target of rapamycin kinase)
Diseases named in the same sentence as MTOR in open-access papers (continued):
Sharing a sentence is not in itself a finding about the gene and the disease.
tumor (continued). "These facts prompted us to study the connection amongst Survivin, P-gp, and PI3K/Akt/mTOR pathway in the MDR of tumor cells." (PMID 35047507, 2021). "Taken together, these findings highlight the potential role of mTOR signaling in the differentiation and recruiting pro-tumorigenic MDSCs cells to dictate an immunosuppressive tumor environment." (PMID 35250965, 2021). "Intraperitoneal administration of rhein inhibited HCT116 xenograft tumor growth through the mTOR pathway." (PMID 33946531, 2021). "Next, we demonstrated that higher POSTN expression promoted angiogenesis in vivo in an RCC xenograft tumor via activating IKL /AKT/mTOR pathway." (PMID 34093819, 2021). "It is well documented that Tan-IIA plays an anti-tumor role by regulating the PI3K/Akt/mTOR signaling pathway." (PMID 34588580, 2021). "In the co-culture system, the relative protein level of p-mTOR (Ser2448) was higher in B16 cells, CT26 cells, and MC38 cells than in AD cells, indicating that mTOR activation is increased in tumor cells." (PMID 34712612, 2021). "All these results support the notion that exosomal miR‐21‐5p derived from MSCs exerts tumour promoter properties in OS by down‐regulating PIK3R1 so as to activate the PI3K/Akt/mTOR signalling pathway." (PMID 34741385, 2021). "Protein kinase B (PKB) and mammalian target of rapamycin (mTOR) are elicited by the binding of tumor antigens to the T cell receptor (TCR) of Tregs." (PMID 34830312, 2021). "In fact, the tumor-suppressive effect of miR-100 has long been recognized to lie in its targeting effect on mTOR expression in tumor cells, thereby modulating chemo- and radio-sensitivities." (PMID 33915898, 2021). "A study also showed that ridaforolimus inhibits mTOR activity, and thus, tumor cell proliferation and VEGF production." (PMID 33925400, 2021). "Sensitivity of RTK-driven tumor models to zotatifin correlated with high basal levels of mTOR activity and elevated translational capacity highlighting the unique circuitry generated by the RTK-driven signaling pathway." (PMID 34900714, 2021). "Of note, recently, studies have described intrinsic effects of PD-L1 engagement in tumor cells through the mammalian target of rapamycin (mTOR) pathway, thus involving PD-L1 in metabolism, autophagy, cell growth and metastatic capability of tumor cells." (PMID 33800368, 2021). "For example, PI3K/mTOR inhibitor PF-05212384 enhanced the antitumor effect and reduced tumor metastasis in head and neck squamous cell carcinoma in vivo." (PMID 34683963, 2021). "The hyperactivation of PTEN/PI3K/AKT/mTOR pathway in bladder cancer plays a central regulatory role in aerobic glycolysis, thereby promoting tumor metabolic switch and tumor cell proliferation." (PMID 34922556, 2021). "Mechanistically, we showed that FeSiNTs/siSPAG5 repressed PI3K/AKT/mTOR signaling, which suppressed the growth and progression of tumor cells." (PMID 34162370, 2021). "Potentiating benefits of mTOR inhibitors in combination with modulators of immune checkpoints have been reported in experimental tumor models." (PMID 33802831, 2021). "In contrast, other driver mutations, such as MTOR, PTEN, SETD2, and KDM5C, exhibited intra-tumor heterogeneity." (PMID 34575959, 2021). "The use of ER stress inducing agents and mTOR inhibitors seems to be the first type of chemotherapy to induce tumor shrinkage in aggressive mouse model of MPNST, making it the most promising therapeutic strategy." (PMID 34502310, 2021). "AT1R also promotes the secretion of matrix metalloproteinases and then activates the PI3K/Akt/mTOR pathway to promote tumor growth and inhibit cell apoptosis." (PMID 33842335, 2021). "In this way, as mTOR is activated during protein synthesis, the increased p-mTOR/mTOR ratio (1.4-fold in AW and 1.8-fold in WW rats) likely suggests a higher liver activity in these tumour-bearing animals." (PMID 34940589, 2021).
tumor (continued). "Samples harboring alterations in the DNA damaging repair (DDR), Notch, PI3K/mTOR, RTK/RAS/RAF, and Wnt pathways exhibited significantly higher blood tumor mutational burden (bTMB) than their wildtype counterparts." (PMID 34335926, 2021). "LAT1 is a plasma membrane transporter for branched-chain amino acids (BCAAs) such as leucine and isoleucine, thereby promoting tumor growth by activating mTOR signaling." (PMID 34780467, 2021). "Collectively, these data demonstrated that mTOR inhibition reduces tumor growth and the fraction of CSCs in MEC." (PMID 33479203, 2021). "The dual PI3K/mTOR inhibitor BEZ235 demonstrates anti-tumour activity in vitro and in vivo in GC models." (PMID 33933113, 2021). "Mutations of TTF1, MTOR, and BAI3 and deletions of CDKN2A were cross-validated to be enriched in the micropapillary tumor components using Asian and European patient cohorts." (PMID 34221970, 2021). "Activation of the PI3-K/Akt/mTOR signaling pathway induces a number of oncogenic processes that contribute to the growth, survival, and proliferation of tumor cells, for example cyclins, C-MYC and ornithine decarboxylase." (PMID 33539381, 2021). "Jointly, these observations demonstrate that curcumin regulates the Akt/mTOR signaling pathway through autophagy to inhibit tumor growth." (PMID 34402718, 2021). "All studies showing benefits of combining anti-tumor vaccines with mTOR inhibitors followed a protocol where mTOR inhibitors were given after or on the same day as vaccination." (PMID 33802831, 2021). "Previously, our research group has proved that biguanide derivatives can exert anti-tumor effects through AMPK/mTOR pathway." (PMID 34641319, 2021). "It is possible that Parkin-mediated regulation of mTOR signaling contributes to its tumor suppressive function." (PMID 33670113, 2021). "A recent study summarized that the mTOR signaling pathway of tumor cells in the tumor microenvironment promoted the tumorigenesis and development by affecting tumor immunity." (PMID 33546704, 2021). "Several papers have shown that in MB the PI3K/AKT/mTOR pathway specifically controls proliferation and survival of tumor stem cells." (PMID 34395258, 2021). "Previous studies have reported alterations in the phosphoinositide 3-kinase (PI3K)/Akt/mTOR signaling pathway, which acts in a proto-oncogene manner and has attracted attention as a target for molecular biomarker-based and targeted tumor therapies." (PMID 34500742, 2021). "Tumor cells overexpressing T cell immunoglobulin mucin-4 (TIM-4) activate PI3K/AKT/mTOR signal transduction and recruit TAMs, promoting proliferation and tumor matrix remodeling in CRC." (PMID 34326840, 2021). "An inhibitory synergistic effect in PDAC cell lines, including patient-derived xenografts and tumor-derived organoids, was observed when N6L was combined with mTOR inhibitors." (PMID 34638443, 2021). "Tumor progression via downstream activation of the PI3K/AKT/mammalian target of rapamycin (mTOR) signaling cascade is thereby induced and further promoted by viral oncoproteins E5, E6 and E7 in HPV-associated malignancies." (PMID 34830902, 2021). "GSEA showed that mTOR and other tumor-related signaling pathways were differentially enriched in the high COPB2 expression phenotype." (PMID 33824874, 2021). "PI3K/AKT/mTOR activation has been reported to trigger hypoxia-inducible factors, contributing to tumor progression and survival by regulating the transcription of oncogenes and GLUTs." (PMID 33849427, 2021). "Studies have demonstrated that mTOR-mediated glycolysis plays an important role in the tumor cell proliferation and migration." (PMID 33771982, 2021). "To further investigate the potential mechanisms of this effect of QFG on CRC tumor, we examined the expression of major regulatory factors involved in the mTOR signal pathway which major regulated EMT and autophagy progression." (PMID 34887935, 2021).
tumor (continued). "The results suggest that the mTOR inhibitor targets both tumor cells and LECs for inhibition of lymphangiogenesis in pNET." (PMID 33128283, 2021). "As a typical tumor suppressor gene that inhibits the cascade of PI3K/AKT/mTOR pro-growth signals, PTEN dysfunction leads to misadjustment of this pathway and other pathways, leading to excessive growth." (PMID 34533198, 2021). "Yet, recent studies showed that other structurally related antipsychotic phenothiazine derivatives also induced autophagy in tumor cells in vitro through the inhibition of PI3K/AKT/mTOR." (PMID 33923896, 2021). "Pretreatment of HCC cells with PI3K/AKT/mTOR inhibitors largely blocked the tumor-promoting effect of CD36." (PMID 33771982, 2021). "M60 presented additional pathogenic alterations of the DNA damage response (DDR) pathway, and F75 showed pathogenic mutations in multiple tumor suppressor genes, such as DEPDC5 p.W905*, an mTOR inhibitor, and several nuclear DNA effectors." (PMID 33853673, 2021). "The Akt/mTOR signaling pathway plays an essential role in the targeting of metabolism by resveratrol in tumor therapy." (PMID 33430318, 2021). "In MB, the PI3K/AKT/mTOR pathway is often deregulated, contributing to the tumor development through the control of cell proliferation, chemoresistance and metastasis." (PMID 34395258, 2021). "Gln catabolism is regulated by the mTOR/Myc axis, which leads to increased protein synthesis and is involved in not only supporting tumor growth and proliferation, but also regulating immune responses." (PMID 33923299, 2021). "Tuberous sclerosis complex (TSC) is a rare multi-systemic autosomal-dominant genetic disease caused by activation of mammalian target of rapamycin (mTOR) complex by mutation of TSC1 and TSC2 genes, characterized by benign tumor growth." (PMID 34332630, 2021). "Further studies showed that the inhibitory effects of puerarin on PCCs were abolished by a mTOR activator, indicating a crucial role of mTOR in anti-tumor effects of puerarin in PDAC." (PMID 34863080, 2021). "The PI3K/Akt/mTOR pathway plays a key role in tumor formation, metabolism, cell cycle progression, apoptosis, survival." (PMID 33967754, 2021). "In particular, the phosphatidylinosito-kinase (PI3K)/protein kinase B (Akt)/mammalian target of rapamycin (mTOR) signaling pathway is one of the many mechanisms regulating cell cycle and apoptosis, wherein an abnormality in any of this pathway's components may cause tumour development." (PMID 34512817, 2021). "The anti-tumor immune cell activity interrupted by PD-L1 is suggested to be mediated by activation of the Akt-mTOR signaling pathway." (PMID 34163519, 2021). "It is well known that Cyclin D1, c-Myc and Cox2 can promote the proliferation of tumor cells while PTEN can suppress the PI3K/AKT/mTOR signaling." (PMID 34026596, 2021). "In particular, dose and administration schedule will be important as degree and timing of mTOR inhibition positively or negatively impact the anti-tumor immune response." (PMID 33802831, 2021). "One the one hand, it has been documented that the PAX3/7–FOXO1 fusion in RMS tumor cells results in constitutively active mTOR signaling." (PMID 34205996, 2021). "Classically, rapamycin has been used as an immunosuppressant agent to prevent organ transplant rejection, but now it is also being employed as a tumour suppressor against mTOR." (PMID 34439105, 2021). "We took in silico, biochemical, in vitro cell culture, and in vivo tumor model approaches to demonstrate that the flavonoid molecule taxifolin can inhibit mTOR and PI3K signaling, promote autophagy, and inhibit lipid synthesis in GBM tumor cells." (PMID 34462635, 2021). "BTK and Akt/mTOR signaling have been previously shown to maintain CSCs population and drive a tumor vascularization response." (PMID 34577576, 2021).
tumor (continued). "The PI3K AKT mTOR signaling pathway can inhibit cell apoptosis, promote tumor cell invasion and metastasis, and regulate angiogenesis, thus contributing to the formation of HCC." (PMID 35127491, 2021). "We found that 47.1% of HCC patients have reduced LIS1 expression, suggesting that LIS1 has a tumor suppressing role in mTOR-driven tumors." (PMID 34348664, 2021). "The activation of PI3K/AKT/mTOR pathway has been commonly considered as a sign of tumor development and deterioration." (PMID 34488535, 2021). "Integrated pathway analysis of DE genes and phosphorylation-dependent proteins predicted an impact on mTOR signalling in BMI1High;CHD7Low MB, a modulation that is also observed in tumour samples with the same signature." (PMID 33846320, 2021). "The exact change in mTOR expression (an 11.88 fall in gene expression) was also revealed in ccRCC, depending on the tumor size." (PMID 34563045, 2021). "We found that the subtype-1 tumours expressed significantly higher levels of several proteins, including mTOR, E-Cadherin, and Raf-pS338, compared to the subtype-2 tumours." (PMID 34506537, 2021). "A study using murine cancer models showed a combination of MEK and PI3K/mTOR inhibitor resulted in significant tumor regression and survival advantages in both basal-like and HER2+ subtype models." (PMID 34026830, 2021). "Mammalian target of rapamycin (mTOR) complexes are in a central regulatory position in signalling networks, including metabolic rewiring in the course of tumour development." (PMID 34360785, 2021). "Western blot analysis showed that sempervirine inhibited AKT/mTOR signaling pathways in tumor tissues." (PMID 34916946, 2021). "A recent report demonstrated that IGF-1–stimulated F-actin reorganization and cell motility occurs via the upregulation of RhoA protein expression and activity through the mTOR signaling pathway in tumor cells." (PMID 34627341, 2021). "This provided a partial explanation to the re-sensitization of Osimertinib since PDCD4 is a major tumor suppressor to repress several oncogenic cascades such as c-Myc, Bcl-xL, and mTOR/Akt." (PMID 34885115, 2021). "Activation of mTOR, among many other effects, inhibits autophagy, which is a cell survival mechanism in general, and in tumor cells in particular." (PMID 34944946, 2021). "Mammalian target of rapamycin (mTOR) signaling was verified to play pivotal roles in tumor cell migration and invasion." (PMID 33494763, 2021). "Together, the data suggested BI853520 suppressed primary tumor proliferation in vivo through PI3K/AKT/mTOR signaling pathway." (PMID 35201437, 2021). "It was found that miR-27a negatively regulates AMPK and positively regulates mTOR pathway to force anaerobic glycolytic metabolism supporting tumour growth and chemoresistance." (PMID 34733591, 2021). "Subsequently, the inhibitory effects of RAD001 were examined on mTOR signalling by staining tumour sections for p‐mTOR expression." (PMID 34120414, 2021). "In contrast, genes related to mammalian target of rapamycin (mTOR), tumor progression, the cell cycle and metastasis/angiogenesis were downregulated." (PMID 33435572, 2021). "Telmisartan treatment reduced tumor volumes in ESCC/EAC xenograft mouse models by regulating the AMP-activated protein kinase (AMPK)/mammalian target of rapamycin (mTOR) transduction pathway and inducing cell cycle arrest." (PMID 34831211, 2021). "Evidence of a crucial role for sirolimus in the PI3K/AkT/mTor pathway has stimulated interest in its involvement in neoplasia, either as monotherapy or in combination with other antineoplastic agents." (PMID 33808416, 2021). "At present, many studies have shown that in a variety of tumors, the mTOR level of tumor tissues and its upstream and downstream molecules are changed." (PMID 34732698, 2021). "Markedly, the expression of PPT1 and p-mTOR decreased in tumor cells derived from erianin-treated mice, as shown by the reduced brown staining." (PMID 35004674, 2021).
tumor (continued). "As expected, the results show that phospho-mTOR was significantly overexpressed in tumor tissues (p < 0.0001)." (PMID 33824874, 2021). "The analysis of tumour tissues from HCC patients revealed that mTOR signalling activity was observed in almost 50% of HCC samples." (PMID 34419152, 2021). "Akt is a protein kinase B that, when stimulated, upregulates mechanistic target of rapamycin (mTOR), which contributes to many growth processes of cells and further contributes to tumor proliferation." (PMID 33920789, 2021). "Drugs targeting the PI3K/AKT/mTOR signaling pathway have had good anti-proliferative, pro-apoptotic, and synergistic effects in tumor radiotherapy and chemotherapy." (PMID 34665844, 2021). "It prevents tumor growth in wild-type mTOR expressing cells and in cells with acquired resistance to the first and the second generation of mTOR inhibitors." (PMID 33946916, 2021). "Blocking the PI3K/AKT/mTOR signaling pathway can inhibit tumor cell proliferation and metastasis and even induce cell apoptosis." (PMID 34675984, 2021). "In combination with the autophagy inhibitor CQ, TSA synergistically exerts anti-tumor activity in H-ras transformed breast epithelial cells by blocking the mTOR-signaling pathway." (PMID 34575981, 2021). "Western blot analysis revealed that phosphorylation of AKT and mTOR in tumor infiltrated TIGIT+ T cells was significantly activated by anti-TIGIT plus anti-PD-1 treatments." (PMID 34659197, 2021). "Altered gene expression in the mTOR signaling pathway in both tumor subtypes highlights the potential benefit from AKT/mTOR inhibitors in IMPCs similarly to IBC-NSTs." (PMID 34531452, 2021). "mTOR is well known to promote tumor growth but its roles in enhancing chemotherapy and radiotherapy have not been well studied." (PMID 33640883, 2021). "It is also known that PD-L1 expression stimulates glycolysis and Akt/mammalian target of rapamycin (mTOR) activation in tumor cells while suppressing this pathway in the T cell counterpart." (PMID 33418913, 2021). "AATs play important roles in AA‐dependent mTOR signaling and tumor cell growth, since they increase the cellular uptake of AAs across the plasma membrane, for example via members of the SLC1, SLC7, and SLC38 family." (PMID 34003553, 2021). "We also observed that inhibition of mTOR showed signs of tumor regression, despite the fact that this study was short-term (7 days) and not designed to measure effects on tumor volume (focus was on CSC effects)." (PMID 33479203, 2021). "Our findings demonstrated that 12‐LOX promoted proliferation and angiogenesis of ESCC tumours via the PI3K/AKT/mTOR pathway both in vitro and in vivo." (PMID 34120414, 2021). "mTOR signalling has previously been highlighted as being of possible relevance in radiosensitivity as a cellular marker of stress in the tumours of patients undergoing chemoradiotherapy." (PMID 34256782, 2021). "Consistent findings were also revealed upon further investigation in vivo, where the concurrent inhibition of GLI and PI3K/AKT/mTOR signaling in mouse subcutaneous xenograft model enhances tumors’ sensitivity to cisplatin, as indicated by reduced tumor burden." (PMID 34572373, 2021). "ANXA1 inhibits autophagy by activating PI3K/Akt/mTOR pathway, leading to the up‐regulation of tumor cell migration and invasion capabilities, EMT‐like changes, and metastasis in vivo." (PMID 34977870, 2021). "In turn, activated AMPK is responsible for orchestrating a tumor-suppressive response that includes a mammalian target of rapamycin (mTOR) inhibition and autophagy initiation." (PMID 33482921, 2021). "PI3K-Akt-mTOR is an important metabolic signaling pathway, which is aberrant expression in a variety of tumor cells." (PMID 34552869, 2021).